PAK1 (p21 (RAC1) activated kinase 1)
Diseases named in the same sentence as PAK1 in open-access papers (continued):
Sharing a sentence is not in itself a finding about the gene and the disease.
hepatocellular carcinoma (25 papers, 2012 to 2024). A malignant tumor that arises from hepatocytes. "In hepatocellular carcinoma, PAK1 is overexpressed together with Snail; further, PAK1 deficiency reduces cancer cell proliferation, migration, and invasion and induces apoptosis." (PMID 38188678, 2023). "Moreover, a decreased expression of Pak1 was observed in cancer-associated cachectic muscles from Yoshida hepatoma-bearing rats and colon adenocarcinoma C26-bearing mice." (PMID 34220542, 2021). "Although we have identified that Klotho expression confers hepatoma cells with resistance to anoikis through VEGFR2/PAK1 activation, the underlying molecular mechanism for Klotho-mediated VEGFR2/PAK1 activation remains still obscure and needs further exploration." (PMID 23516476, 2013). "The involvement of PAK1 as a promoter of cell proliferation has been widely described in hepatocytes and hepatocellular carcinoma." (PMID 35625715, 2022). "HBV infection results in an enhancement of PAK1 transcription, which confers resistance of hepatoma cells to anoikis, a form of apoptosis that involves cells detaching from their extracellular matrix." (PMID 28430160, 2017). "Axitinib treatment sensitized anoikis was reversed by constitutive active mutant PAK1 T423E coexpression in Klotho-overexpressed hepatoma cells." (PMID 23516476, 2013). "TUNEL assay revealed that increased anoikis by VEGFR2 inhibitor Axitinib or its blocking antibody was partially blunted by PAK1 activation with PAK1 T423E cotransfection in Klotho-overexpressed hepatoma cells." (PMID 23516476, 2013). "Colony formation assay showed that increased anchorage-independent growth of hepatoma cells due to Klotho expression was reversed by inactivating PAK1 kinase activity with PAK1 K299R cotransfection or IPA3 treatment." (PMID 23516476, 2013). "Colony formation assay showed that inhibited anchorage-independent growth by VEGFR2 inhibitor Axitinib or its blocking antibody was partially reversed by PAK1 activation with PAK1 T423E cotransfection in Klotho-overexpressed hepatoma cells." (PMID 23516476, 2013). "In our previous studies, we have identified PAK1 activation is crucial for resistance of hepatoma cells to anoikis." (PMID 23516476, 2013). "The importance of anoikis resistance in liver cancer metastasis was elegantly shown in our previous studies where p21-activated kinase 1 (PAK1) has been identified as a key mediator for hepatoma resistance to anoikis." (PMID 23516476, 2013). "Taken together, these results suggest that VEGFR2/PAK1 signaling dominates Klotho-induced resistance of hepatoma cells to anoikis." (PMID 23516476, 2013). "Annexin V/PI staining, Caspase 3/7 activity assay, and TUNEL assay in suspended hepatoma cells showed that Klotho-induced anoikis resistance was reversed by inactivating PAK1 kinase activity with PAK1 K299R cotransfection or IPA3 treatment." (PMID 23516476, 2013). "Caspase 3/7 activity assay revealed that increased anoikis by VEGFR2 inhibitor Axitinib or its blocking antibody was partially reversed by PAK1 activation with PAK1 T423E cotransfection in Klotho-overexpressed hepatoma cells." (PMID 23516476, 2013). "For instance, PAK1, which signals downstream of Cdc42 and Rac, was shown to be overexpressed in hepatocellular carcinoma and expression of PAK1 was furthermore shown to correlate with the metastatic potential of this cancer type." (PMID 22623902, 2012). "In hepatocellular carcinoma, anoikis resistance of hepatoma cells has been determined to require PAK1 activity, and CAV1 could also confer resistance of hepatoma cells to anoikis by activating the IGF‐1 pathway." (PMID 36507553, 2023). "Mitochondrial-localized PAK1 interacts with Bcl2 to allow hepatoma cells to become resistant to anoikis which might promote progression of HCC in patients with chronic HBV infection." (PMID 34456908, 2021).
hepatocellular carcinoma (continued). "In particular, in hepatocellular carcinoma cells, AXL induces cell migration via activation of PI3K, and subsequent AKT- and GTPase-independent stimulation of p21 (RAC1) activated kinase 1 (PAK1), a critical kinase implicated in cytoskeleton remodeling and control of directional motility." (PMID 34638349, 2021). "PAK1 activation has consistently been shown to promote anoikis resistance in hepatoma cells." (PMID 25093037, 2014). "Consistent with our previous studies indicating the pivotal significance of PAK1-induced anoikis resistance in HBV-associated hepatocarcinogenesis, our current data also indentify VEGFR2/PAK1 activation as downstream effector of Klotho expression in anoikis resistance of hepatoma cells." (PMID 23516476, 2013). "We also provide evidence that Klotho expression confers hepatoma cells with resistance to anoikis via activating VEGFR2/PAK1 signaling, which could be reversed by inhibition with PAK1 allosteric inhibitor IPA3 or VEGFR2 inhibitor Axitinib administration in Klotho-overexpressed hepatoma cells." (PMID 23516476, 2013). "Other studies have indicated that PAK1 activation promotes metastasis of osteosarcoma, as well as Ra1-PAK1 signaling in EMT in human hepatocellular carcinoma." (PMID 37190165, 2023). "PAK6, a homologous protein of PAK1, was shown to be epigenetically regulated by the PRC2 complex in hepatocellular carcinoma." (PMID 36478132, 2023). "P21-activated kinase 1 (PAK1), one of the serine/threonine kinases, is widely overexpressed in various human cancers, including hepatic carcinoma." (PMID 32587849, 2020). "Besides, we have also provide evidence that VEGFR2/PAK1 inhibition with VEGFR2 inhibitor Axitinib, or anti-VEGFR2 blocking antibody, or PAK1 allosteric inhibitor IPA3 administration could significantly blunt anoikis resistance in Klotho-overexpressed hepatoma cells." (PMID 23516476, 2013). "Klotho overexpression elevated p21-activated kinase 1 (PAK1) expression and shRNA-mediated PAK1 knockdown and kinase activity inhibition with kinase dead mutant PAK1 K299R coexpression or allosteric inhibitor IPA3 treatment reversed anoikis resistance in Klotho-overexpressed hepatoma cells." (PMID 23516476, 2013). "Furthermore, Klotho expression conferred hepatoma cells with resistance to anoikis via activating VEGFR2/PAK1 signaling, which could be reversed by inhibition with PAK1 allosteric inhibitor IPA3 or VEGFR2 inhibitor Axitinib administration in Klotho-overexpressed hepatoma cells." (PMID 23516476, 2013).
ovarian carcinoma (21 papers, 2014 to 2025). A malignant neoplasm originating from the surface ovarian epithelium. "In this research, we found that the expression of PAK1 correlated with an unfavorable prognosis in ovarian cancer." (PMID 42017177, 2025). "The PAK1/β-catenin pathway, demonstrated in ovarian cancer, influences EMT by modulating β-catenin activity through cytoskeletal remodeling, while the Wnt/β-catenin pathway is a canonical signaling cascade implicated in cell proliferation and differentiation." (PMID 40296944, 2025). "In ovarian cancer, it suppresses proliferation and epithelial-mesenchymal transition (EMT) via the p21-activated kinase 1 (PAK1)/β-catenin pathway, while its knockdown enhances cisplatin sensitivity in ovarian cancer cells by inhibiting proliferation and EMT." (PMID 40296944, 2025). "It had been reported that ivermectin inhibited breast and ovarian cancer cells proliferation by promoting PAK1 ubiquitination degradation and cytostatic autophagy by suppressing Akt/mTOR signaling pathway." (PMID 34876051, 2021). "Ivermectin can also inhibit the cells growth of human ovarian cancer through blocking the oncogenic kinase PAK1." (PMID 34876051, 2021). "Upregulation of PAK1 was reported in diverse human cancers, such like thyroid cancer, ovarian cancer, bladder cancer and TSCC." (PMID 32190006, 2020). "We have recently identified Pak1 and Pak4 as prognostic markers and potential therapeutic targets for ovarian cancer." (PMID 26218748, 2015). "Pak1 and Pak4 promote ovarian cancer cell migration and invasion through the p38/VEGF pathway and the c-Src/MEK-1/MMP2 pathway, respectively." (PMID 26218748, 2015). "In ovarian cancer, expression levels of PAK1, PAK2 and their phosphorylated forms were upregulated in both cell lines and clinical samples." (PMID 25093037, 2014). "In search of the functional effect of PAK1 in ovarian cancer, knockdown of PAK1 markedly inhibited cell motility and invasiveness, accompanied by suppressed p38 activity and VEGF expression." (PMID 25093037, 2014). "Depletion of PAK1, introduction of a kinase-dead mutation, or treatment with the inhibitor IPA-3 could reduce HR repair efficiency and increase ovarian cancer cell sensitivity to the PARP inhibitor olaparib." (PMID 42017177, 2025). "Nonetheless, whether PAK1 also affects HR repair and PARPi sensitivity in ovarian cancer remains unresolved." (PMID 42017177, 2025). "Collectively, our findings suggest that targeting PAK1 might offer a new avenue for increasing the sensitivity of olaparib and improving the outcomes of ovarian cancer patients." (PMID 42017177, 2025). "The PAK1/β-catenin pathway also plays an essential role in ovarian cancer." (PMID 32863957, 2020). "Knockdown of Pak1 and Pak2 in ovarian cancer cell lines reduced cell migration and invasion." (PMID 25050916, 2014). "Finally, our experiments showed that MIIP could reduce MMP9, which is consistent with the recent report of Rac1/Pak1/p38/MMP axis in ovarian cancer oncogenesis." (PMID 27760566, 2016). "DOCK7 has also been reported to be highly expressed in ovarian cancer, and is recruited into the nucleus by MDC1 to participate in the DNA damage response through the RAC1/CDC42/PAK1 module." (PMID 38385857, 2024). "Although the role of PAK1 in tumor angiogenesis has not been studied in detail, one study does suggest a role for PAK1 in the regulation of tumor angiogenesis in ovarian cancer." (PMID 37190165, 2023). "Overexpression of PAK1 and PAK2 has been found in ovarian cancer cells." (PMID 35501919, 2022).
prostate carcinoma (21 papers, 2012 to 2025). A carcinoma that arises from epithelial cells of the prostate gland. "Elevated PAK1 protein levels are associated with colorectal, hepatocellular, and prostate cancer metastasis, and PAK2 and 6 overexpression is linked to chemotherapeutic and radiation resistance in breast and prostate cancers, respectively." (PMID 29875996, 2018). "Two specific mutations found in prostate cancer enhance RhoD binding and one other mutation results in loss of inhibition of Rac-dependent Pak1 phosphorylation and lamellipodia formation and in impairment of trafficking of plexinB1 to the membrane." (PMID 22404908, 2012). "However, further work is required to elucidate the functional difference between nuclear and cytoplasmic VAV3, which is reminiscent of the results for PAK1 and could be linked to the activation of the androgen receptor, as previously shown in prostate cancer." (PMID 24886537, 2014). "This process results in the CK2-mediated phosphorylation of PAK1 at Ser223, leading to full PAK1 activation, as observed in prostate cancer cells." (PMID 40001545, 2025). "Studies on PAK1 have been conducted mostly in gastrointestinal tract tumors, as well as in ovarian, head and neck, pancreatic, and prostate cancers." (PMID 40864802, 2025). "Further support for a role for PAK1 in advanced prostate cancer can be seen by the fact that higher levels of PAK1 mRNA expression in PCa patients correlate with higher Gleason scores, as compared to low-grade PCa." (PMID 37190165, 2023). "Our recent studies showed that prostate cancer cells expressing higher levels of PAK‐1 were resistant to the cytotoxic effects of the PAK‐1 inhibitor, inhibitor targeting PAK‐1 activation‐3 (IPA‐3), compared to those with lower expression." (PMID 31516713, 2019). "Given the significant roles of FMNL1 and PAK1—two molecules involved in actin polymerization and cell motility—we hypothesized that their expression levels would be elevated in prostate cancer patients, particularly in advanced stages." (PMID 40864802, 2025). "The second and third ranks belonged to the papers entitled “Dissecting the association between Metabolic Syndrome and Prostate Cancer” (AAS = 393) and “Liposome-mediated delivery of the p21 activated kinase-1 (PAK-1) inhibitor IPA-3 limits prostate tumor growth in vivo”, respectively (ASS = 202)." (PMID 40115019, 2025). "A recent report showing that PAK1 signaling is critical to medulloblastoma cell migration suggests that reduced PAK1 activity mediated through Rac1 inhibition in our prostate cancer model may also account for the suppressed cell migration observed." (PMID 24040362, 2013). "In support of this, our results suggest that PAK1 acts downstream of Rac and Cdc42 to promote actin polymerization, filopodia formation and cancer cell invasion, showing that F-actin reorganization plays a major role in cell movement in prostate cancer cells." (PMID 24040362, 2013). "In the current study, we determined whether over-expression and dimerization of protein 14-3-3ζ leads to Rac1-mediated activation of Pak1/2 in prostate cancer cells." (PMID 22808202, 2012). "PAK1 could be further investigated as a potential therapeutic target of prostate cancer." (PMID 28186966, 2017). "Another interesting protein in this context is PAK1, which interacts with CTNNB1 and has already been described as a potential target for prostate cancer." (PMID 38927982, 2024). "We previously designed novel liposomal formulations targeting both PAK-1 and sPLA2, called Secretory Phospholipase Responsive liposomes or SPRL-IPA-3, and demonstrated their ability to alter prostate cancer growth." (PMID 33321758, 2020). "In this study on prostate cancer, we investigated FMNL1 and PAK1 in prostate cancer patients." (PMID 40864802, 2025).
prostate carcinoma (continued). "Our study manifested that PAK1 expression were increased in prostate cancer tissues compared with BPH, and PAK1 mRNA and protein in DU145 and PC-3 were obviously higher than LNCaP and RWPE-1, respectively, in addition, PAK1 expression was increased in DU145 compared with PC-3." (PMID 28186966, 2017). "On the other hand, although the MEK/ERK MAPK pathway is known for its role in cell proliferation, there is little evidence that MAPK activity is increased in prostate cancer and interactions between Rac1/PAK1 and MEK/ERK is likely to be cell type-dependent." (PMID 24040362, 2013). "Since PAK1 can also regulate cell transformation and survival and because of increased frequency of phosphorylation observed in poor outcome tumors, the PAK signaling pathway could therefore constitute a major effector pathway of Rac1/Cdc42 in prostate cancer cells." (PMID 24040362, 2013). "In addition, ERK activity was not affected by Rac1 inhibition in lymphoma cells further suggesting that this Rac1 targeting strategy exerts its effect via modulation of the PAK1-AKT signaling pathway, but not the MAP kinases, to affect prostate cancer cell proliferation." (PMID 24040362, 2013).
non-small cell lung carcinoma (16 papers, 2015 to 2025). A group of at least three distinct histological types of lung cancer, including non-small cell squamous cell carcinoma, adenocarcinoma, and large cell carcinoma. "Simultaneously, PAK1 is believed to promote the proliferation and invasion of non-small cell lung cancer cells through the ERK pathway." (PMID 40332759, 2025). "For example, ERK and AKT signaling pathways are suppressed by the inhibition of PAK1, which decreases the non-small cell lung cancer cell proliferation and invasion." (PMID 34876240, 2021). "p21-activated kinase 1 (PAK1) stimulates growth and metastasis in non-small cell lung cancer (NSCLC)." (PMID 31660987, 2019). "Here we investigated the role of PAK1/Crk axis in transduction of the oncogenic KRAS signal in non-small cell lung cancer (NSCLC)." (PMID 25956913, 2015). "Moreover, miR-615-5p acted as a tumor suppressor in non-small cell lung cancer by regulating P21-Activated Kinase 1 (PAK1)." (PMID 39789663, 2025). "Similarly, the inhibition PAK1-regulated Wnt/β-catenin pathway also enhanced the sensitivity of cancer cells to Cisplatin in non-small cell lung cancer." (PMID 32863957, 2020). "However, a role for PAK1 in the chemoresistance observed in non-small cell lung cancer (NSCLC) remains to be elucidated." (PMID 27713506, 2016). "In non-small-cell lung cancer (NSCLC), the up-regulation of transforming growth factor-β receptor type 1 (TGFBR1) can also stimulate the activation of PAK1 to promote tumorigenesis." (PMID 32863957, 2020). "Non-Small Cell Lung Cancer (NSCLC): In NSCLC cells, irradiation increases the expression of PAK1." (PMID 36830998, 2023). "Similarly, overexpression of PAK1 also correlates with aberrant expression of EMT markers and poor prognosis in non-small cell lung cancer." (PMID 30971268, 2019). "Similarly, we speculate that PAK1 also facilitates proliferation and invasion by reducing the extent of CD8-positive T cell infiltration in non-small cell lung cancer." (PMID 40332759, 2025).
breast tumors (14 papers, 2008 to 2024). "In addition, it has been shown that a gene encoding one member of the PAK family, PAK1, located on human chromosome 11q13, is amplified and/or overexpressed in several human cancer types, including 25-30% of breast tumor samples and cancer cell lines." (PMID 27740936, 2016). "PAK1 is amplified in several human cancer types, including 30-33% of breast tumor samples and cancer cell lines (, reviewed in(Eswaran, Li, Shah, & Kumar, 2012; Kumar, Gururaj, & Barnes, 2006; Molli, Li, Murray, Rayala, & Kumar, 2009))." (PMID 38660565, 2024). "In this study we aimed to assess PAK1 gene copy number (CN) in primary breast tumours and their corresponding lymph node metastases, and associations between PAK1 CN and proliferation status, molecular subtype, and prognosis." (PMID 37368917, 2023). "Our IHC analysis revealed that anti-myc signal was detected in breast tumor (B) of myc-PAK1 WT- and myc-PAK1 Y3F-inoculated mice (C) as well as in lung of myc-PAK1 WT-inoculated mice (D) but not in lungs of control GFP- (E) or PAK1 Y3F-inoculated mice (F)." (PMID 27542844, 2016). "The gene encoding the serine-threonine protein kinase p21-activated kinase 1 (PAK1) is amplified and/or overexpressed in several human cancer types including 25-30% of breast tumors." (PMID 27740936, 2016). "PAK1 overexpression was observed in over half of observed breast tumor specimens and PAK1 expression is correlated with tumor grade." (PMID 27542844, 2016). "The finding of elevated Pak1 expression in some of our cell lines mirrors the observation that Pak1 is sometimes upregulated in breast tumors." (PMID 19317917, 2009). "In one breast tumor, we found a very narrow 11q14 amplicon that did not include the PAK1 gene." (PMID 24367492, 2013).